RPA2 (replication protein A2)
Diseases named in the same sentence as RPA2 in open-access papers (continued):
Sharing a sentence is not in itself a finding about the gene and the disease.
myelodysplastic syndrome (1 paper, 2023). A clonal hematopoietic disorder characterized by dysplasia and ineffective hematopoiesis in one or more of the hematopoietic cell lines. "Because germline RPA1 mutations are linked to early onset TBD with predisposition to myelodysplastic syndromes, we interrogated pediatric cancer cohorts to define the prevalence and spectrum of rare/novel and putative damaging germline RPA1, RPA2, and RPA3 variants." (PMID 37869077, 2023).
non-small cell lung carcinoma (1 paper, 2025). A group of at least three distinct histological types of lung cancer, including non-small cell squamous cell carcinoma, adenocarcinoma, and large cell carcinoma. "Treatment of non-small cell lung cancer cells with 6 mM ascorbate increased the expression of γ-H2AX, p-Chk1, and p-RPA2, and disrupted the accumulation of DNA repair factors at damaged sites via H2O2 production." (PMID 39990670, 2025).
parathyroid adenoma (1 paper, 2023). "Based on our findings, the plausible explanation of the pathogenesis of multiple endocrine type-1 associated parathyroid adenoma could be conformational changes in S606F mutated menin that strongly stabilized the extended binding with RPA2, thereby hindering the binding of NF-κB." (PMID 37291166, 2023).
pulmonary fibrosis (1 paper, 2021). Chronic progressive interstitial lung disorder characterized by the replacement of the lung tissue by connective tissue, leading to progressive dyspnea, respiratory failure, or right heart failure. "Most importantly for the topic of pulmonary fibrosis, reconstitution of RAGE restores DNA DSBs repair, thus reverses pulmonary fibrosis, in part, by promoting efficient RPA2 and CHK1 phosphorylation, required for efficient DNA repair and prevention of senescence." (PMID 34899603, 2021).
serous ovarian cancers (1 paper, 2026). "High nuclear RPA1 and RPA2 protein was significantly associated with high grade serous ovarian cancers (HGSOC), advanced stage, platinum resistance and worse progression free survival (PFS) (all ps <0.05)." (PMID 41702233, 2026).
thyroid cancer (1 paper, 2024). "NHEJ- (XRCC6, XRCC5, PRKDC) and HR- (SSBP1, SEM1, RPA2, RPA3) related genes are expressed by both normal follicular and thyroid cancer cells." (PMID 38380364, 2024). "NHEJ- (XRCC6, XRCC5, PRKDC) and HR‐ (SSBP1, SEM1, RPA2, RPA3)-related genes were found to be expressed in both normal follicular and thyroid cancer cells." (PMID 38380364, 2024).
xeroderma pigmentosum group D (1 paper, 2021). Any xeroderma pigmentosum in which the cause of the disease is a mutation in the ERCC2 gene. "A point mutation in xeroderma pigmentosum group D (XPD) enhances its processivity similarly to replication protein A 2 (RPA2)." (PMID 33739282, 2021). "RPA2 increases xeroderma pigmentosum group D (XPD) helicase processivity." (PMID 33739282, 2021). "Xeroderma pigmentosum group D (XPD) exhibits two burst types, the fraction of which is replication protein A 2 (RPA2) dependent." (PMID 33739282, 2021). "Xeroderma pigmentosum group D (XPD) unwinds in bursts of varying processivity whose average increases with replication protein A 2 (RPA2) concentration." (PMID 33739282, 2021). "Replication protein A 2 (RPA2) transiently melts hairpin duplex but does not assist xeroderma pigmentosum group D (XPD) unwinding." (PMID 33739282, 2021).
cancer (20 papers, 2008 to 2025). A tumor composed of atypical neoplastic, often pleomorphic cells that invade other tissues. "The authors of these studies concluded that the SNP variants influenced miRNA-mediated regulation of GTF2H1 and RPA2 mRNA levels and thus DNA repair activity and the cancer risk." (PMID 32629861, 2020). "We first demonstrate that we can reliably evaluate replication stress in FFPE cancer cells with an antibody targeting Thr21-phosphorylated RPA2 (p-RPA2)." (PMID 40392598, 2025). "In our assay, RAD51 and p-RPA2 staining only produces foci if the cancer cells recently experienced HR and replication stress, thereby providing a dynamic reading of both processes." (PMID 40392598, 2025). "Herein, we focused on the in silico investigation of dual targeting of the proteins RPA2 and MLH1, which are implicated in several cancer-relevant DDR pathways." (PMID 38137049, 2023). "RPA2 overexpression has been observed in many cancers, suggesting its potential role as a prognostic factor." (PMID 38137049, 2023). "By mining the Catalogue Of Somatic Mutations In Cancer (COSMIC) database, we found that somatic mutations in RPA1, RPA2, RPA3 are found in 1.4%, 0.5%, and 0.9% of human cancers, respectively." (PMID 37869077, 2023). "To address this knowledge gap, we investigated the occurrence of novel and rare germline variants in RPA1, RPA2 and RPA3 genes, in a cohort of 5,993 children with cancers." (PMID 37869077, 2023). "We found that RAD52 readily partitions into phase-separated RPA droplets in vitro, and that RAD52 enrichment at sites of ALT activation is reduced in cancer cells expressing phase-separation-impaired, phosphomimetic RPA2." (PMID 36894693, 2023). "An analysis of Cancer Cell Line Encyclopedia data showed that, like mPTCL, human T‐cell lymphoma lines tend to express higher levels of RPA2 (RPA32) and CHEK1 compared with all cancer cell lines overall." (PMID 35510955, 2022). "Consistent with previous findings that greater clonal diversity has been associated with a higher likelihood of therapy-resistant and metastatic subpopulations, we found that patients with heterogeneous RAD51 and p-RPA2 staining in their cancers exhibited the worst survival outcomes." (PMID 40392598, 2025). "Although our data illustrate a clear association between therapy response and p-RPA2 foci, the mechanisms driving high p-RPA2 in some cancers are not fully elucidated." (PMID 40392598, 2025). "Based on these data, we reasoned that germline defects in RPA1 and possibly also the other 2 components of the RPA heterotrimer (RPA2 and RPA3) might be associated with cancer development." (PMID 37869077, 2023). "In contrast, none of EA80 VUS targeted phosphorylation sites of RPA (N-terminal of RPA2), critical for DNA damage response and indicator of cancer progression: this implies that phosphorylation regulation is critical for cancer development and viability." (PMID 34966786, 2021). "Overexpressed RPA1 and/or RPA2 are detected in various cancers, suggesting that RPA may be useful as a prognostic marker in cancer patients." (PMID 34316690, 2020). "We further evaluated whether USP52 phosphorylation by ATM affects CHK1 and RPA2 phosphorylation and render cells resistant to cancer therapy." (PMID 33097710, 2020). "A way to modulate RPA–protein interactions in cancer cells, and thereby to disrupt DDR activation, is via specific inhibitors that target the N-terminus or RPA1 (70N) and the C-terminus of RPA2 (32C), which harbor the protein interaction modules." (PMID 34316690, 2020). "Within the pan-cancer cohort, we identified 80 cases with 55 germline heterozygous RPA1, RPA2 or RPA3 variants meeting criteria of AF < 0.5% in gnomAD non-cancer cohort and CADD score > 15 for candidate variant selection." (PMID 37869077, 2023).
cancer (continued). "The RPA (human replication protein A) family, including RPA1, RPA2, and RPA3, plays an essential role in eukaryotic DNA replication, homologous recombination, and excision repair; it has been recognized as an oncogene and therapeutic target for cancer." (PMID 37091868, 2023). "Compared with Genome Aggregation Database (gnomAD) non-cancer controls, there was significant enrichment of ultra-rare and novel RPA1, but not RPA2 or RPA3, germline variants in our cohort (adjusted p-value < 0.05)." (PMID 37869077, 2023). "Finally, since RPA2 is extensively phosphorylated in cancer cells with high levels of replication stress and abrogated CHK1, it can be used as a predictive biomarker in cancer therapy protocols utilizing CHK1 inhibitors." (PMID 34316690, 2020). "Thus, the concurrent targeting of both RPA2 and MLH1 could increase the efficacy of radiotherapy in cancers in which RPA inhibition alone has shown poor results, assuming intolerable toxicity for organisms; the latter merits further investigation." (PMID 38137049, 2023). "To confirm whether transient ALT/telomeric HR-repair is involved in the processing of X-rays-induced DNA damage at telomeres, we checked some of the hallmarks used to define ALT in cancer cells such as TSCE and colocalization of PML (or RPA2) with telomeric DNA." (PMID 31336873, 2019). "The expression levels of FANCD2, TP53BP1, and RPA2 were statistically significantly elevated in HGD and in carcinomas, according to the results of non-parametric Friedman tests." (PMID 36061145, 2022).
tumor (18 papers, 2009 to 2026). "Low RPA2 was significantly associated with larger tumours, high grade, de-differentiation, pleomorphism, high mitotic index, high Ki67 index, lympho-vascular invasion, lymph node positivity and high-risk Nottingham Prognostic Index (NPI) (all P values ≤0.01)." (PMID 36997566, 2023). "In the whole cohort, Low RPA2 mRNA was significantly associated with poor overall survival in the whole cohort (P < 0.0001), in ER + tumours (P < 0.0001) and ER- tumours (P = 0.013)." (PMID 36997566, 2023). "Previous studies have shown the interaction of RPA2 with menin for the maintenance of tumor suppressive activity." (PMID 37291166, 2023). "The combination of VPA and HU has been demonstrated to have a synergistic effect in killing tumor cells, the molecular mechanism of action involves inhibition of Replication Protein A2 (RPA2) hyperphosphorylation-mediated DNA repair pathway." (PMID 34513672, 2021). "Using GO biological process enrichment analysis, we found that CUL1, CUL3, RNF2, and RPA2 overlap in their mitotic cell cycles, which has important biological implications in tumor development." (PMID 32170141, 2020). "In IBC, low RPA2 protein expression was observed in 54% (782/1444) of tumours." (PMID 36997566, 2023). "Given that RPA2 expression in ascites tumor cells (5-year survival rate, 0.83 vs 0.68, P = 0.724; median PFS, 11.3 months vs. 19.8 months, P = 0.418) was weakly correlated with poor prognosis of HGSC patients in training cohort, it was not included in subsequent analyses." (PMID 35392433, 2022). "The interaction between tumor cells and brain cells contributes to a microenvironment that supports BC growth by secreting factors such as ERH, RPA2, S100A9, and nerve growth factor inducible (VGF)." (PMID 39712454, 2025). "They found that miR-519 inhibits the growth and survival of tumor cells via repressing the expression of proteins involved in DNA maintenance (including DUT1, EXO1, RPA2, and POLE4) and intracellular calcium homeostasis (ATP2C1 and ORAI1)." (PMID 37601663, 2023). "In the same hospital, significantly different expressions between matched tumour and healthy adjacent tissues were observed for 6 genes (APEX1, DDB1, ERCC1, NEIL1, PARP1, RPA2) after snap freezing collection." (PMID 27383461, 2016). "Thus, RPA2 and RPA3 could be considered as genes of unknown significance (GUS) yet potentially important in tumor formation." (PMID 37869077, 2023). "In addition, we analysed the gene expression data of HNSC cases in the TCGA data set, which suggested that RPA1 and RPA3 were up‐regulated in HNSC tissues compared with non‐tumour tissues, whereas RPA2 expression did not significantly differ between HNSC and non‐tumour tissues." (PMID 28557284, 2017). "Concurrently, BC cells secrete factors like ERH, RPA2, and S100A9, which are not normally present in the brain, thereby enhancing tumor proliferation." (PMID 39712454, 2025).
infection (4 papers, 2017 to 2025). The state of being infected such as from the introduction of a foreign agent such as serum, vaccine, antigenic substance or organism. "Infection by Ra led to the formation of distinct nuclear pRPA2 and RPA2 foci and robust activation of ATR-Chk1 pathway, suggesting that Ra induces generation of ssDNA." (PMID 32223892, 2020). "Consistent with a role for activated ATR during infection, we found that Ser33 in RPA2, an ATR substrate, becomes phosphorylated in an ATR-dependent manner from 4 hr post-infection at the time of genome replication." (PMID 28467896, 2017). "Host proteins enriched at cellular replication forks during infection included DNA processing factors such as GINS, TOP2A, PRIM1/2, RPA2 and XRCC1; DDR signaling proteins such as CSNK2A1/3; cell cycle regulator proteins such as TFDP2 and SFN1; as expected for cells undergoing replication stress." (PMID 40825038, 2025). "In vitro, it was found that P+ group could induce DNA damage in OSCC cells under short-term acute infection, which made γ-H2AX gradually accumulate with cell proliferation, activate the upstream signal molecule of ATR-CHK1, and increase the phosphorylation level of ATR and RPA2." (PMID 34660289, 2021).
CNS tumors (1 paper, 2023). "Statistical analysis using two- and one-sided Fisher exact tests of ultra-rare plus novel and rare germline heterozygous variants in RPA1, RPA2 and RPA3 across hematologic, extra-cranial solid and CNS tumors." (PMID 37869077, 2023).
hematological malignancies (1 paper, 2023). "Germline heterozygous variants found in RPA1, RPA2 and RPA3 in pediatric hematological malignancies." (PMID 37869077, 2023). "Besides these descriptions associating germline RPA1 variants with bone marrow failure or hematologic malignancies, the RPA2 or RPA3 genes have not been linked to any human diseases thus far." (PMID 37869077, 2023).
RPA2 also shares sentences with these, for which no sentence is quoted: Fanconi anemia (2 papers); melanoma (2); xeroderma pigmentosum group A (2); diffuse large B-cell lymphoma (1); endometrial cancer (1); glioma (1); hepatocellular carcinoma (1); Hodgkins lymphoma (1); lymphoma (1); medulloblastoma (1); rectal carcinoma (1); sarcoma (1); spinal muscular atrophy (1); spinocerebellar ataxia type 1 (1); Wilms tumor (1); xeroderma pigmentosum group C (1).